APTR (Alu-mediated CDKN1A/p21 transcriptional regulator)
Synonyms: RSBN1L-AS1
Gene: Long non-coding RNA gene on chromosome 7 (77,657,659 to 77,697,074, reverse strand). Ensembl gene ENSG00000214293.
Diseases named in the same sentence as APTR in open-access papers:
APTR is named in the same sentence as 13 diseases in open-access papers, as found by Europe PMC text mining. Sharing a sentence is not in itself a finding about the gene and the disease. The quoted sentences say what the papers report.
liver fibrosis (4 papers, 2018 to 2024). "Elevated APTR expression was observed in two mouse models with liver fibrosis induced by CCl4 and bile duct ligation, as well as in humans with liver fibrosis of an unspecified aetiology." (PMID 39872125, 2024). "In the mouse liver fibrosis model, APTR accelerates cell cycle and promotes HSC proliferation through negatively regulating p21." (PMID 30931332, 2019). "Given the weak primary sequence conservation of lncRNAs compared with protein-coding genes, the consistent APTR expression patterns observed in mice and humans across different aetiologies of liver fibrosis indicate the potentially crucial role of APTR in liver fibrosis." (PMID 39872125, 2024). "Furthermore, APTR silencing attenuates liver fibrosis in CCl4-treated mice." (PMID 30931332, 2019). "Because primary sequence conservation of lncRNAs is weak when compared to protein-coding genes, findings of similar APTR expression patterns in mice and humans, independent of the underlying etiology of liver fibrosis, is interesting and warrant further investigation." (PMID 30134610, 2018). "Knockdown of APTR using adenovirus in CCl4-treated mice resulted in reduced levels of αSMA and COL1A1, and mitigated liver fibrosis." (PMID 39872125, 2024).
osteosarcoma (3 papers, 2021 to 2023). A usually aggressive malignant bone-forming mesenchymal neoplasm, predominantly affecting adolescents and young adults. "APTR/miR‐132‐3p/YAP1 is a possible functional axis participating in the pathogenesis of osteosarcoma." (PMID 34094972, 2021). "As another core ferroptosis-related lncRNA noted in this study, APTR has been shown to reduce miR-132-3p and enhance YAP1 expression, which in turn promotes osteosarcoma progression." (PMID 36923797, 2023).
leiomyoma (2 papers, 2021 to 2024). A well-circumscribed benign smooth muscle neoplasm characterized by the presence of spindle cells with cigar-shaped nuclei, interlacing fascicles, and a whorled pattern. "In leiomyomas, the lncRNA APTR is overexpressed and enhances cell proliferation by activating the Wnt/β-Catenin pathway through targeting estrogen receptor alpha (ERα)." (PMID 39519092, 2024). "In conclusion, our data suggest that APTR promoted leiomyoma cell proliferation through the Wnt pathway by targeting ERα, suggesting a new role of APTR in the Wnt signaling pathway in UL." (PMID 33777725, 2021). "Given the recently identified role of APTR, we first detected APTR expression in leiomyoma tissues and adjacent normal tissues." (PMID 33777725, 2021).
anaplastic thyroid cancer (1 paper, 2021). "Downregulation of APTR has been correlated with tumorigenesis in papillary thyroid cancer and anaplastic thyroid cancer." (PMID 33777725, 2021).
breast carcinoma (1 paper, 2021). "GATA3 is another target genes of miR-132-3p based on miRTArbase and miRWalk databases, therefore APTR/miR132-3p/GATA3 is another possible route of participation of APTR in breast cancer." (PMID 34094972, 2021). "Based on the observed correlation between APTR and ESR1 in the current study, APTR/miR-9/ESR1 is another putative functional axis in breast cancer." (PMID 34094972, 2021). "Thus, APTR/miR132-3P/FOXA1 axis possibly contributes in the pathogenesis of breast cancer." (PMID 34094972, 2021). "Therefore, in addition to the connection between APTR and ER signaling, over-expression of this lncRNA in breast cancer cells might facilitate the development of this cancer via repression of miR-132-3p expression." (PMID 34094972, 2021). "Then, we determined five lncRNAs with a putative role in breast cancer using the LncRNA disease (v.3.0) database, including AC144450.1, APTR, RAMP2-AS1, LINC00663, and ZNF337-AS1." (PMID 34094972, 2021). "Moreover, expression levels of APTR, AC144450.1, and ZNF337.AS1 were elevated in breast cancer tissues compared with control tissues." (PMID 34094972, 2021). "Moreover, expression levels of APTR, AC144450.1, and ZNF337.AS1 were elevated in breast cancer tissues compared with control tissues (RME = 2.27, P value = 5.40E−03; Ratio of mean expressions = 615.95, P value = 7.39E−19 and RME = 1.78, P value = 3.40E−02, respectively)." (PMID 34094972, 2021).
breast neoplasm (1 paper, 2021). A benign or malignant neoplasm of the breast parenchyma. "The current investigation suggests future assessment of the functional role of APTR, AC144450.1 and ZNF337.AS1 in the development of breast neoplasms." (PMID 34094972, 2021).
gastric cancer (1 paper, 2024). A primary or metastatic malignant neoplasm involving the stomach. "In addition, downregulation of lncRNA APTR has been confirmed to be closely related to the diagnosis and prognosis of gastric cancer, and knockdown of APTR was conducive to the proliferation and migration of gastric cancer cells." (PMID 38627627, 2024).
prostate carcinoma (1 paper, 2014). A carcinoma that arises from epithelial cells of the prostate gland.
cancer (3 papers, 2018 to 2021). A tumor composed of atypical neoplastic, often pleomorphic cells that invade other tissues. "Most of these identified lncRNAs were reported in cancer for the first time, except APTR (Alu-mediated p21 transcriptional regulator)." (PMID 30205363, 2018). "APTR represses the CDKN1A/P21 promoter, which has been correlated with cell proliferation in several cancers." (PMID 33777725, 2021).
tumor (3 papers, 2014 to 2023). "The expression of APTR in OS tumor tissues and four OS cell lines (MG63, 143B, Saos-2 and HOS) was significantly up-regulated compared with that of in neighboring tissues and human osteoblast cell lines hFOB1.19, respectively." (PMID 37858131, 2023). "We found that lncRNA Alu-mediated p21 transcriptional regulator (APTR) showed higher expression in UL tumor tissues compared with that in normal uterine tissues." (PMID 33777725, 2021).
APTR also shares sentences with these, for which no sentence is quoted: glioblastoma (1 paper); infection (1); papillary thyroid cancer (1).